PSMB9 (proteasome 20S subunit beta 9)
Description:
The proteasome is a multicatalytic proteinase complex which is characterized by its ability to cleave peptides with Arg, Phe, Tyr, Leu, and Glu adjacent to the leaving group at neutral or slightly basic pH. The proteasome has an ATP-dependent proteolytic activity. This subunit is involved in antigen processing to generate class I binding peptides. Replacement of PSMB6 by PSMB9 increases the capacity of the immunoproteasome to cleave model peptides after hydrophobic and basic residues.
Synonyms: LMP2; PSMB6i; RING12; beta1i; PRAAS3; PRAAS6
Tractability: Small molecule: an approved drug acts on it; a structure with a bound ligand is known; a high-quality ligand is known; it belongs to a druggable protein family. PROTAC: ubiquitination databases record sites on it; its protein half-life has been measured; a small molecule that binds it is known.
Target class: Threonine protease; Protease; Enzyme; Threonine protease PBT clan; Threonine protease T1B subfamily
Chemical probes: CHEMBL3319604, KZR-504 (high quality)
Gene: Protein-coding gene on chromosome 6 (32,844,136 to 32,860,734, forward strand). Ensembl gene ENSG00000240065.
Subcellular location: Cytoplasm; Nucleus
Subcellular location (Human Protein Atlas): Cytosol
Pathways (Reactome):
Immune System: Antigen processing: Ub, ATP-independent proteasomal degradation; Cross-presentation of soluble exogenous antigens (endosomes); ER-Phagosome pathway
Metabolism of proteins: Proteasome assembly
Gene Ontology:
Molecular function: protein binding; endopeptidase activity; threonine-type endopeptidase activity
Biological process: proteasome-mediated ubiquitin-dependent protein catabolic process; CD8-positive, alpha-beta T cell differentiation; CD8-positive, alpha-beta T cell homeostasis; immune system process; negative regulation of regulatory T cell differentiation; positive regulation of interleukin-2 production; positive regulation of tumor necrosis factor production; positive regulation of type II interferon production; proteasomal protein catabolic process; response to type II interferon; T-helper 1 cell differentiation; T-helper 17 cell differentiation; thymic T cell selection; protein catabolic process
Cellular component: cytosol; extracellular exosome; proteasome complex; nucleus; proteasome core complex; proteasome core complex, beta-subunit complex; spermatoproteasome complex; cytoplasm
Genetic constraint (gnomAD): Loss-of-function variants: 16 observed, 26.37 expected, observed/expected ratio (o/e) 0.61, 90% interval 0.41 to 0.92. The upper end of that interval is the gene's LOEUF score, 0.92, which puts it in group 3 of 6, group 1 being the genes least tolerant of losing a copy. Missense variants: 253 observed, 294.44 expected, observed/expected ratio (o/e) 0.86, 90% interval 0.77 to 0.95. Synonymous variants: 91 observed, 109.84 expected, observed/expected ratio (o/e) 0.83, 90% interval 0.7 to 0.99.
Homologues: Orthologues: chimpanzee PSMB9 (99% identical), macaque PSMB9 (97% identical), pig PSMB9 (95% identical), mouse Psmb9 (88% identical), guinea pig PSMB9 (88% identical), dog PSMB9 (86% identical), rat Psmb9 (77% identical), tropical clawed frog psmb9 (68% identical), zebrafish psmb9a (64% identical), Drosophila melanogaster Prosbeta1 (49% identical), Caenorhabditis elegans pbs-1 (42% identical). Paralogues in human: PSMB6 (59% identical), PSMB8 (31% identical), PSMB10 (30% identical), PSMB7 (30% identical), PSMB11 (27% identical), PSMB5 (26% identical), PSMB1 (25% identical), PSMB2 (21% identical), PSMB4 (21% identical), PSMB3 (21% identical), PSMA4 (20% identical), PSMA6 (19% identical), and 6 more.
Diseases named in the same sentence as PSMB9 in open-access papers:
PSMB9 is named in the same sentence as 187 diseases in open-access papers, as found by Europe PMC text mining. Sharing a sentence is not in itself a finding about the gene and the disease. The quoted sentences say what the papers report.
melanoma (20 papers, 2010 to 2025). A malignant, usually aggressive tumor composed of atypical, neoplastic melanocytes. "Higher expression of PSMB9 in melanoma tumors has been linked with better patient outcomes while lower expression levels in NSCLC cells exhibited better prognosis." (PMID 34944095, 2021). "IFN-γ increases the levels of the immunoproteasome subunits PSMB8 and PSMB9, whereas increased expression of these genes stimulates anti-melanoma IFN-γ production by tumor-infiltrating lymphocytes, which is associated with an enhanced response to ICIs." (PMID 40108693, 2025). "Collectively, these data highlight the therapeutic value of increasing the expression levels of TAP1, TAP2, TAPBP and PSMB9 in melanoma." (PMID 36458012, 2022). "By verifying the immunotherapy effect of PSMB9 in the melanoma cohort, we proved its promising prospect as a tumor immunotherapy target." (PMID 35928883, 2022). "We divided the cohort into two subgroups according to the expression of PSMB9, and we performed the survival curves that identified that the higher expression of PSMB9 predicts a better prognosis in patients with melanoma." (PMID 35928883, 2022). "The β1i subunit, encoded by PSMB9, was found to be reduced in breast cancer, renal cell carcinoma, APL, and NSCLC while elevated in melanoma and ovarian cancer." (PMID 34944095, 2021). "Immunoproteasome expression was evaluated as a predictive marker for immune checkpoint blockade therapy in melanoma, with high expression of PSMB8 and PSMB9 associated with better response to anti-PD-1 and anti-CTLA-4 treatment." (PMID 34944095, 2021). "To assess the relationship between the expression levels of immunoproteasome subunits PSMB8 and PSMB9 and melanoma patient survival, we analyzed data from TCGA of 472 melanoma patients for whom RNA-seq data and patient outcome were available." (PMID 32060274, 2020). "We describe here that the overexpression of PSMB8 and PSMB9, two major components of the immunoproteasome, is predictive of better survival and improved response to immune-checkpoint inhibitors of melanoma patients." (PMID 32060274, 2020). "However, within the 26S proteasome, large variability was observed for the protein complex subunits PSMB9 and PSMB8 of the immunoproteasome, the expression of which is associated with immune response to ICBs in melanoma." (PMID 38047086, 2023). "To test our hypothesis that overexpression of IP subunits derives alternative, more immunogenic peptides, we overexpressed both PSMB8 and PSMB9 (OE) or a vector control (EV) in three different melanoma cell lines (108T, 12T and A375)." (PMID 32060274, 2020). "Importantly, we find that PSMB8 and PSMB9 expression levels are much stronger predictors of melanoma patientsʼ immune response to checkpoint inhibitors than the tumors’ mutational burden." (PMID 32060274, 2020). "The insights gathered through these analyses suggest that the expression levels of immunoproteasome subunits PSMB8 and PSMB9 can serve as biomarkers for predicting survival of melanoma patients and for identifying patients likely to favorably respond to immune-checkpoint inhibitors." (PMID 32060274, 2020). "Here, the authors demonstrate that a high expression of the two major components of the immunoproteasome, PSMB8 and PSMB9, modulates the production of HLA peptides and it is predictive of better survival and improved response to immune-checkpoint inhibitors of melanoma patients." (PMID 32060274, 2020). "Hypomethylation-induced PSMB9 upregulation enhanced CD8+ activation, boosted IFN-γ signaling, and suppressed melanoma cell proliferation and migration." (PMID 41293269, 2025). "PSMB9 upregulated via hypomethylation, enhanced CD8+ activation, IFN-γ signaling; inhibited melanoma proliferation/migration." (PMID 41293269, 2025). "A recent retrospective study on immune checkpoint therapy response for NSCLC and melanoma cohorts delineated a genetic signature of antigen processing and presentation (APM) genes which included PSMB9." (PMID 34944095, 2021).
melanoma (continued). "Higher APM scores, and higher PSMB9 expression, correlated with better responses for immune checkpoint therapy (ICB) in both NSCLC and melanoma with improved overall survival." (PMID 34944095, 2021). "This is the first report to establish the association between the overexpression of immunoproteasome subunits PSMB8 and PSMB9 and improved survival and enhanced response to immune-checkpoint inhibitors (both anti-CTLA4 and anti-PD1) in melanoma patients." (PMID 32060274, 2020). "In addition, analysis of gene expression in melanoma biopsies revealed an IFN-γ-related methylation subtype, which included high expression of PSMB9 and was characterized by increased OS in patients." (PMID 40108693, 2025). "To test this hypothesis, we utilized HLA peptidomics to analyze the changes in the HLA peptide repertoire of melanoma cells due to PSMB8 and PSMB9 overexpression and determined the effects of these changes on the reactivity of patient infiltrating tumor lymphocytes (TILs)." (PMID 32060274, 2020).
breast carcinoma (14 papers, 2006 to 2025). "Next, we wanted to determine if the samples that contained more PSMB8 + cells also contained more PSMB9 + cells and found a strong correlative association for all breast cancer subtypes together, as well as for TNBC specifically." (PMID 36746983, 2023). "Intriguingly, all CRLM of patient II (favorable outcome) were characterized by a strikingly high expression of the WNT pathway-related immunoproteasome gene PSMB9, which has been associated with enhanced lymphocyte infiltration and longer survival in breast cancer patients." (PMID 35565214, 2022). "We analyzed a prognostic model based on seven DDR genes, PSMD2, PSMD7, PSMD14, PARP3, MDC1, PSMB1, and PSMB9, reflecting an enhanced level of predicting the survival and prognosis of patients with breast cancer." (PMID 37350936, 2023). "Here, we sought to determine the impact of PSMB8 and PSMB9 expression at the protein level on outcomes in breast cancer and TNBC patients, but also in the context of the cell type expressing the ImP proteins." (PMID 36746983, 2023). "In contrast, the expression levels of PARP3 and PSMB9 were lower in breast cancer cells than in normal cells." (PMID 37350936, 2023). "Previously, we observed in a basal breast cancer network a module formed by PSMB9, TAP1, and UBE26 genes among others." (PMID 30761130, 2019). "To investigate if the revealed differences in gene expression correlate with the amount of proteasome subunits in cancer cells, we analyzed the relative levels of mRNAs encoding the immunoproteasome subunits PSMB8, PSMB9 and PSMB10 in four breast cancer cell lines: MCF-7, SKBR3, ZR-75-1 and BT-474." (PMID 39796785, 2025). "Interestingly, while the quantities of PSMB8- or PSMB9-positive cells increased significantly with the grade of the disease, the number of immune cells remained the same for grade 1 and 2 breast cancers and decreased for grade 3." (PMID 36746983, 2023). "For PSMB9, the study found that PSMB9 was overexpressed in breast cancer cells." (PMID 37609286, 2023). "Our results show significant benefits, notably in terms of relapse-free survival (RFS), as well as metastasis to bones and liver, with increased expression of both PSMB8 and PSMB9 by tumor cells, particularly in the context of basal-like breast cancer and TNBC." (PMID 36746983, 2023). "NR1H3 is a nuclear receptor component and an anti-invasive gene for bladder cancer; PARP12 has been reported to suppress hepatocellular carcinoma metastasis; SAMHD1 is yet another suppressor of epithelial transformation; PSMB9 is a key metastasis suppressor for breast cancer." (PMID 33562461, 2021). "Along these lines, it has been shown that Ki-67 knockout breast cancer cells demonstrate decreased expression of PSMB8 and PSMB9." (PMID 39796785, 2025). "The protein levels of MDC1, PSMB1, PSMB9, PSMD2, PSMD7, and PSMD14 were increased, while that of PARP3 was decreased in breast cancer tissues compared with normal tissues." (PMID 37350936, 2023). "In order to determine the impact of ImP expression on breast cancer outcomes, we assessed the protein expression and cellular source of the ImP subunits PSMB8 and PSMB9 in a cohort of 2070 patients." (PMID 36746983, 2023). "Subsequently, we explored the protein levels of MDC1, PARP3, PSMB1, PSMB9, PSMD2, PSMD7, and PSMD14 in normal breast tissues and breast cancer tissues." (PMID 37350936, 2023). "Our analysis revealed no advantage to either PSMB8 or PSMB9 overexpression when considering all breast cancer subtypes together, as well as for the luminal A or luminal B subtypes specifically." (PMID 36746983, 2023). "Our findings were similar when assessing the overall survival (OS) with high PSMB8 and PSMB9 mRNA expression being particularly important for basal-like breast cancers and important but not statistically significant for TNBC." (PMID 36746983, 2023).
breast carcinoma (continued). "Furthermore, when analyzing whether CD45 and PSMB8 or PSMB9 expression were linked, we found an inverse correlation, therefore suggesting that increased ImP expression is not positively linked to immune cell infiltration in our breast cancer patient cohort." (PMID 36746983, 2023). "We established a seven-gene prognostic model comprising MDC1, PARP3, PSMB1, PSMB9, PSMD2, PSMD7, and PSMD14 genes, which provides a basis for further exploration of a population-based prediction of prognosis and immunotherapy response in patients with breast cancer." (PMID 37350936, 2023). "Also, for a small cohort of breast cancer patients, estrogen receptor alpha-negative tumors (which include TNBCs) for which PSMB9 expression was elevated had slower tumor growth." (PMID 36746983, 2023).
lymphoma (13 papers, 2017 to 2025). A malignant (clonal) proliferation of B- lymphocytes or T- lymphocytes which involves the lymph nodes, bone marrow and/or extranodal sites. "Psmb9 and Psmb8 are genes encoding immunoproteasome subunits that act upstream or within antigen processing, bacterial presentation, and response, and have been implicated in both lymphoma and renal cell carcinoma." (PMID 37193034, 2023). "PSMB9 expression was relatively higher in brain cancer, head and neck cancer, bile duct cancer, kidney cancer, leukemia, lymphoma, and myeloma, among which lymphoma showed the highest expression." (PMID 41020834, 2025). "To investigate the impact of tumor-intrinsic PSMB9 expression on CD19 CAR-T cell therapy, we first examined PSMB9 protein levels across CD19+ ALL cell line Nalm6 and lymphoma cell lines Raji and Daudi using Western blot analysis." (PMID 41020834, 2025).
COVID-19 (8 papers, 2021 to 2024). A disease caused by infection with severe acute respiratory syndrome coronavirus 2. "Of note, the predicted expression of PSMB9 was significantly associated with seronegativity after the first dose of the COVID-19 vaccine, as revealed by TWAS and replication." (PMID 38181733, 2024). "Here, HSCT, PSMB9, STAT2, and TNFSF13B were identified as common risk genes of AF and COVID-19 patients." (PMID 38025532, 2023). "Regarding the expression of 20S subunits in the α- and β-ring the mRNA expression of PSMA4, PSMA5, PSMB2, PSMB9, PSMB10 significantly increased in COVID-19 patients (COV) when compared to healthy control (HC)." (PMID 35327634, 2022). "Specifically, along with CD68, the immunoproteasome-related genes PSMB8, TAP1, PSMB9, PSMB10, and calreticulin (CALR) were all found to be expressed in the CD14+/CD16+ subpopulation of cells during mild COVID-19." (PMID 34225749, 2021). "On the other hand, higher methylation of PSMB9, MRPS2, MFHAS1, and MAT2B genes are known to be expressed in COVID-19 patients with high viral load or severe infection, which could translate to a lower expression of those genes." (PMID 36371196, 2022). "Besides, the majority of proteasome subunits studied (unless PSMB9 and PSME1) positively correlated with NLRP3 mRNA expression in COVID-19 patients." (PMID 35327634, 2022). "Interestingly, we only observed an increase in PSMB9 and PSMB10, suggesting mediation of the immunoproteasome in COVID-19 pathology." (PMID 35327634, 2022).
glioma (8 papers, 2017 to 2025). A benign or malignant brain and spinal cord tumor that arises from glial cells (astrocytes, oligodendrocytes, ependymal cells). "For instance, in lower-grade glioma tumors, PSMB9 transcript levels were shown to correlate with increased gene signatures for CD8 and CD4 T cells, macrophages, as well as B cells." (PMID 40698074, 2025). "For example, PSMB8 expression decreased survival in gastric cancer and PSMB9 expression correlated with poor outcomes in glioma." (PMID 40698074, 2025). "Notably, in cholangiocarcinoma, ocular melanoma, pancreatic cancer, and glioma, amplification was the sole observed genetic alteration of PSMB9." (PMID 41020834, 2025). "Numerous studies have demonstrated the regulatory roles of PSMB8, PSMB9, and PSMB10 in glioma proliferation, migration, angiogenesis, inflammatory response, and hypoxia-related tumor characteristics." (PMID 39619148, 2024).
ovarian carcinoma (8 papers, 2016 to 2025). A malignant neoplasm originating from the surface ovarian epithelium. "It is also noteworthy that PSMB9 expression is up-regulated by GCS overexpression in ovarian cancer, and is associated with cancer resistance to platinum-based chemotherapy." (PMID 40507922, 2025). "The CpG mutation of PSMB9 is related to the recurrence or drug resistance of ovarian cancer after chemotherapy." (PMID 34109184, 2021). "Treatment of cancer cells with 5-AC also leads to significant re-expression of B2M, CALR, CD58, PSMB8, and PSMB9 at both the RNA and protein level in the colon and ovarian cancer cell lines." (PMID 28622390, 2017). "Eight immune factors (IFT57, MAL, ANXA4, SCRN1, LTBR, KIFAP3, HSPA5, and LTN1) were positively correlated with poor prognosis of ovarian cancer, whereas six immune factors (PSMB9, FOXJ1, CTSH, MIF, CTSD, and PSMB8) were negatively correlated with poor prognosis of ovarian cancer." (PMID 34109184, 2021). "High expression of PSMB8 and PSMB9 is related to the five-year survival of ovarian cancer." (PMID 34109184, 2021). "We confirm that treatment with DNMT inhibitors upregulates expression of the antigen processing and presentation molecules B2M, CALR, CD58, PSMB8, PSMB9 at the RNA and protein level in a wider range of colon and ovarian cancer cell lines and treatment time points than had been described previously." (PMID 28622390, 2017). "Interestingly, one recent paper found that, DNMT inhibitors (that removed DNA methylation) up-regulate expression of the antigen processing and presentation molecules, including PSMB9 at the RNA and protein level in a wider range of colon and ovarian cancer cell lines." (PMID 31703610, 2019). "The results shown that gene MZB1, HSF1, PIK3R4, PSMB9, RSF1 and SPI1were significantly overexpressed in ovarian cancer cells SKOV-3." (PMID 40424327, 2025).
colitis (7 papers, 2012 to 2024). Inflammation of the colon. "Confirmation qPCR in the ipsilateral hippocampus demonstrated that acute colitis following craniotomy (Sham+DSS) resulted in a trend for increased expression of neuroinflammatory (Tspo, Cybb, Gfap, Psmb9) and neuropathology (Mmp2) genes compared to water-treated Sham mice." (PMID 33461596, 2021).